MAL2 (mal, T cell differentiation protein 2)
Diseases named in the same sentence as MAL2 in open-access papers (continued):
Sharing a sentence is not in itself a finding about the gene and the disease.
breast carcinoma (continued). "Besides, further studies are needed to explore the mechanism of MAL2 in breast cancer." (PMID 34567213, 2021). "Moreover, we found that MAL2 was an independent prognostic factor and might become a biomarker for breast cancer." (PMID 34567213, 2021). "Moreover, MAL2 expression was correlated with the prognosis of breast cancer." (PMID 34567213, 2021). "Besides, MAL2 was recently identified as a breast cancer immunology target." (PMID 34567213, 2021). "However, the relationship between MAL2 and breast cancer requires further investigation." (PMID 34567213, 2021). "MAL2 might be a novel prognostic biomarker of breast cancer." (PMID 34567213, 2021). "However, a further study about the correlation between MAL2 and breast cancer was needed." (PMID 34567213, 2021). "The literature shows that MAL2 protein can interact with MUC1-C and positively regulate its expression in breast cancer." (PMID 36895039, 2023). "In a recent study, using RT-qPCR, two panels of transcripts related to the presence of CTCs (Panel 1: CK19, EpCAM, SCGB2A2 and Panel 2: EMP2, SLC6A8, HJURP, MAL2, PPIC and CCNE2), in two cohorts of breast cancer patients (metastatic and early), were evaluated." (PMID 37046848, 2023). "In line with what we observed in breast cancer, NSMCE2 or MAL2 are significantly higher in the cancer samples compared to the normal corresponding samples in most of the cancer types studied." (PMID 36224576, 2022). "Human T cell differentiation protein 2 (MAL2), a member of the MAL protein family, was initially identified as a partner for tumor protein D52-like proteins in breast carcinoma." (PMID 35437691, 2022). "Through pharmacological SE disruption assays performed in breast cancer cell lines, we experimentally confirmed that SEs regulate the expression of NSMCE2 or MAL2." (PMID 36224576, 2022). "For example, MAL2 and MRPL13 can inhibit tumor antigen presentation to drive breast cancer immune escape, and upregulation of two genes in breast cancer has been demonstrated to drive malignant progression of cancer." (PMID 36267313, 2022). "We found that high transcript levels of 3 genes – NSMCE2, MAL2 and EIF3H – significantly correlate with worse overall survival in breast cancer patients (Log-rank test, p-value < 0.05)." (PMID 36224576, 2022). "Therefore, MAL2 may be a potential therapeutic target and prognostic factor for breast cancer." (PMID 35111745, 2021). "A panel of six genes: CCNE2, DKFZp762E1312, EMP2, MAL2, PPIC, and SLC6A8 that were over-expressed in the blood of 81% of patients with recurrent breast cancer was then chosen as gene markers for the molecular detection of CTC." (PMID 21129172, 2010). "We therefore examined the distribution of MAL2 and MUC1 in Triton X-100-soluble and -insoluble fractions from breast carcinoma cell lines." (PMID 19175940, 2009). "In our present study, we evaluated two panels of transcripts related with the presence of circulating tumor cells (CTCs) (Panel 1: CK19, EpCAM, SCGB2A2 and Panel 2: EMP2, SLC6A8, HJURP, MAL2, PPIC and CCNE2) in two cohorts of breast cancer patients (metastatic and early)." (PMID 36831613, 2023). "Studies have confirmed that MAL2 inhibits the presentation of tumor antigens by directly interacting with MHC-I complexes to promote the endocytosis of tumor antigens, thereby promoting the immune escape of breast cancer cells." (PMID 36895039, 2023). "MAL2 expression was only reduced by BET inhibition in cell lines representing HER2 + and TN breast cancer subtypes, but it was curiously increased after 24 h of treatment in the TN BT549, perhaps as an indirect effect of BET inhibition on downregulating MAL2 repressors." (PMID 36224576, 2022). "As for SLC16A6, CCL5, and MAL2, their protein expression was almost negative in breast cancer tissues based on the results of the HPA database." (PMID 36341328, 2022).
breast carcinoma (continued). "By using this approach, we identified two highly upregulated genes in tumors, NSMCE2 and MAL2, for which high levels of gene expression significantly correlate with breast cancer patients’ negative prognosis." (PMID 36224576, 2022). "Next, we investigated in other cancer types (apart from breast cancer) whether expression of NSMCE2 and MAL2 is higher in tumor samples when compared to normal tissue and whether high levels of any of these two genes associate with poor survival." (PMID 36224576, 2022). "In the present study, the transcript levels of a 6-gene panel (CCNE2, PPIC, MAL2, EMP2, HJURP, and SCL6A8) previously published as candidate CTC markers, and of epithelial cell lineage-specific (EpCAM, CK19) and breast cancer-specific (SCGB2A2) markers were assessed." (PMID 36074219, 2022). "We have shown that the RT-qPCR-based multi-marker analysis using the six genes: CCNE2, DKFZp762E1312, EMP2, MAL2, PPIC, or SLC6A8 more than doubled the number of positive patients with recurrent breast cancer compared to the analysis of hMAM or EpCAM gene expression alone." (PMID 21129172, 2010). "MAL2/MUC1 interactions were detected in Triton X-100-soluble membrane fractions, indicating that MAL2 has specific functions within non-raft membrane compartments in breast cancer cells." (PMID 19175940, 2009). "We also chose these cell lines because NSMCE2 and MAL2 are amplified in all except in MDAMB231 (visualized using cBioPortal on data from the Cell Line Encyclopedia), which recapitulates our observation in breast cancer patients’ datasets where these two genes were frequently amplified." (PMID 36224576, 2022). "Interesting, we found that there was a broad cytoplasmic expression of MAL2 in carcinoma tissues of CRC, while rare in non-cancerous tissues, which was also reported in breast cancer and renal cell cancer, suggesting that the oncogenic function of MAL2 was carried out in the cytoplasm." (PMID 28562687, 2017).
ovarian carcinoma (13 papers, 2009 to 2025). A malignant neoplasm originating from the surface ovarian epithelium. "In our present research, we observed a strong association between MAL2 and the survival rate and gene mutation rate in patients of ovarian cancer (OC)." (PMID 35111745, 2021). "Previous studies have demonstrated increased expression of MAL2 in ovarian cancer, prostate adenocarcinoma, papillary thyroid cancer and pancreatic cancer." (PMID 37480012, 2023). "MAL2 was over-expressed in many human cancers, including breast, stomach, liver, pancreatic, colon, kidney, prostate and ovarian cancers." (PMID 35503998, 2022). "Here, we downloaded data from multiple databases to analyze MAL2 expression and function in pan-cancers, especially in ovarian cancer (OC)." (PMID 35111745, 2021). "Previous studies have confirmed the increased expression of MAL2 in ovarian cancer, pancreatic cancer, thyroid cancer, and colorectal cancer." (PMID 34567213, 2021). "MAL2 binds tumor protein D52 (TPD52),which is over-expressed in ovarian carcinoma, and we have shown that MAL2 isfrequently over-expressed in all histological subtypes of ovarian cancer." (PMID 21423607, 2011). "It was interesting to note that cytoplasmic expression of MAL2 was rare in benign and borderline tumours, but common in ovarian carcinomas." (PMID 20846453, 2010). "The present study has confirmed MAL2 overexpression in ovarian cancer, as predicted by previous expression microarray analyses, and has shown this to be a frequent event." (PMID 20846453, 2010). "Increased MAL2 expression in ovarian cancer has been repeatedly identified by independent expression microarray studies, with two meta-analyses highlighting the same finding." (PMID 20846453, 2010). "The present study has highlighted frequent MAL2 overexpression in ovarian carcinoma, particularly in serous tumours." (PMID 20846453, 2010). "Independent expression microarray studies predict MAL2 overexpression in ovarian carcinoma, but these had remained unconfirmed." (PMID 20846453, 2010). "Furthermore, experimental results showed that MAL2 deletion negatively regulated proliferation, migration, and invasion of ovarian cancer." (PMID 41465326, 2025). "Furthermore, knockout of MAL2 inhibits the proliferation, invasion and migration and promotes apoptosis of ovarian cancer (OC) cells in vivo and in vitro." (PMID 37480012, 2023). "At present, some literatures have reported that TPD52 is highly expressed in ovarian cancer tissues and acts as a downstream signal molecule in some processes, indicating that TPD52 also plays an important role in the occurrence and development of ovarian cancer, and MAL2 and TPD52 are chaperones." (PMID 35111745, 2021). "The frequent overexpression of MAL2 in ovarian carcinoma, coupled with its low expression in benign and borderline lesions, may indicate a potential role for MAL2 in disease detection and/or monitoring, particularly in high-grade serous carcinoma." (PMID 20846453, 2010). "MAL2 binds tumor protein D52 (TPD52), which is frequently overexpressed in ovarian carcinoma, but the clinical significance of MAL2 and TPD52 overexpression was unknown." (PMID 20846453, 2010). "The frequent overexpression of MAL2 in ovarian carcinomas, coupled with its low expression in benign and borderline lesions, suggest that MAL2 may be a useful marker component to assist in disease detection and/or monitoring." (PMID 20846453, 2010). "The aim of the present study was therefore to define MAL2 and TPD52 expression in a large cohort of ovarian carcinomas, relative to other clinical parameters." (PMID 20846453, 2010). "Ovarian cancer patients with high TGFB2 and MAL2 mRNA levels showed the longest OS improvement." (PMID 41465326, 2025).
ovarian carcinoma (continued). "MAL2 (Mal, T Cell Differentiation Protein 2), a transmembrane protein of the MAL proteolipid family, is upregulated in a number of malignancies, such as breast, colorectal, pancreatic, or ovarian cancer, has been shown to correlate with invasion and worse prognosis." (PMID 35445910, 2022). "A panel of six genes: CCNE2, DKFZp1312, PPIC, EMP2, MAL2 and SLC6A8 may serve as potential markers for CTC derived from breast, endometrial, cervical, and ovarian cancers." (PMID 21827674, 2011). "MAL2 is frequently overexpressed in ovarian carcinoma, and TPD52 overexpression is a favourable independent prognostic marker of potential value in the management of ovarian carcinoma patients." (PMID 20846453, 2010). "MAL2 overexpression might also reduce cytoplasmic MUC1 accumulation, which has been indicated to be an adverse finding in breast and ovarian carcinomas, tumor types which also overexpress MAL2." (PMID 19175940, 2009). "However, no study to date has examined whether MAL2 expression is increased in ovarian carcinoma, or its potential clinical significance." (PMID 20846453, 2010).
pancreatic cancer (13 papers, 2009 to 2025). "In pancreatic cancer cell lines, overexpressed MAL2 associated with the scaffolding protein IQGAP1 that, in turn, activated MAPK ERK1/2 signaling." (PMID 37345137, 2023). "MAL2 has been shown to be associated with the prognosis of patients with pancreatic cancer and colorectal cancer, which can affect the overall survival of patients." (PMID 37480012, 2023). "It has been shown that highly metastatic cells demonstrates the overexpression of MAL2 and high expression of MAL2 is associated with a lesser survival of postoperative patients and a high rate of distant metastasis in pancreatic cancer." (PMID 28562687, 2017). "Moreover, MAL2 expression was associated with pancreatic cancer and colorectal cancer overall survival, which suggested that MAL2 might be an important molecule involved in the progression and prognosis of tumors." (PMID 34567213, 2021). "Another example concerning MAL2 relates to the sensitivity of pancreatic cancer cell lines to different chemotherapeutic agents (gemcitabine, 5-fluoruracil and cisplatin)." (PMID 37345137, 2023). "Accumulating investigations pointed out that high MAL2 expression prompted pancreatic cancer progression and predicted adverse survival in patients with pancreatic cancer." (PMID 36522691, 2022). "Results revealed that the MAL2 expression level increased in breast, ovarian, prostate, and pancreatic cancers." (PMID 34567213, 2021). "SCAPM1 suppressed migration and invasion of pancreatic cancer; MAL2 expression predicted distant metastasis in pancreatic cancer." (PMID 31061236, 2019). "Overexpression of MAL2 has also been reported in other cancers, including primary ovarian carcinoma and ascites, and pancreatic carcinoma, where MAL2 has since been employed as a discriminator of pancreatic carcinoma versus chronic pancreatitis." (PMID 19175940, 2009). "MAL2 silencing also affected tumor size in nude mice xenografts of pancreatic cancer cells." (PMID 37345137, 2023). "We determined the genes that express differently in pancreatic cancer tissues compared with normal tissues and associate with survival (P < 0.05) as Hub genes, yielding a total of six Hub genes, including S100A14, KRT8, KRT19, MAL2, MYO5B, and PSCA." (PMID 36522691, 2022). "Also, the high expression of MAL2 contributed to the short survival time and high distant metastasis rate of postoperative pancreatic cancer patients." (PMID 34567213, 2021). "Interestingly, suppression of MUC1 expression in a pancreatic cancer cell line reduced these cells' metastatic potential, and was accompanied by reduced MAL2 levels." (PMID 19175940, 2009). "By combining expression analysis and survival analysis for these lncRNAs in pancreatic cancer using TCGA data, only 4 lncRNAs (SCAMP1, HCP5, MAL2, LINC00511) were defined as the key lncRNAs." (PMID 31061236, 2019). "Only 10 (SCAMP1, EMG1, HCP5, TUG1, MAL2, H19, LINC00511, RP11-311C24.1, RP11-400F19.6 and CTC-459F4.3) out of 90 lncRNAs were significantly upregulated in pancreatic cancer samples when compared with normal controls." (PMID 31061236, 2019). "This is consistent with the previous inclusion of MAL2 in marker panels to discriminate pancreatic cancer from pancreatitis and metastatic from non-affected lymph nodes in colorectal cancer patients." (PMID 20846453, 2010). "The level of MAL2 transcripts is inversely correlated with resistance to these drugs, suggesting that the analysis of MAL2 levels in PAAD could be used as an indicator of the response to chemotherapy in pancreatic cancer." (PMID 37345137, 2023).
bladder cancer (6 papers, 2021 to 2025). "In addition, MAL2 was also highly expressed in bladder tumor cells, and its expression associated strongly with the survival rate and clinicopathological traits of bladder cancer." (PMID 33634966, 2021). "Further mechanism study demonstrated that FTO promoted the tumorigenesis of bladder cancer by suppressing microRNA miR-384 and inducing mal T cell differentiation protein 2 (MAL2) expression." (PMID 35628623, 2022). "In dividing the tissues from cohort 2, the quantification of MAL2 protein expression scores, demonstrated that the protein expression of MAL2 was markedly (p = 0.0044) correlated with the survival rate in the bladder cancer patients." (PMID 33634966, 2021). "FTO facilitates the tumorigenesis of bladder cancer through regulating the MALAT/miR‐384/MAL2 axis in m6A RNA modification manner, which ensures the potential of FTO for serving as a diagnostic or prognostic biomarker in bladder cancer." (PMID 33634966, 2021). "Similarly, FTO-mediated m6A removal in MALAT1 mRNAs activated the MALAT1/miR-384/MAL2 cascade, leading to the development of bladder cancer." (PMID 38556586, 2024). "FTO promotes bladder cancer tumor growth via MALAT1/miR‐384/MAL2 axis." (PMID 33634966, 2021). "The data suggest that MALAT1 may act as a RNA sponge to interact with miR‐384 and further modulation MAL2 expression and promote bladder cancer proliferation." (PMID 33634966, 2021). "MALAT1 and MAL2 interact with miR‐384 for regulating tumor growth of bladder cancer." (PMID 33634966, 2021). "Accordingly, we found that MAL2 silencing could reduce the viability of bladder cancer cells, indicating that it has an oncogenic role in bladder carcinogenesis." (PMID 33634966, 2021). "In addition, a significant correlation was found between MAL2 expression and the smoking status (p = 0.0192) and pathologic stage (p = 0.0104) of the bladder cancer patients in cohort 2 and between MAL2 expression and FTO expression." (PMID 33634966, 2021). "We demonstrate that the mechanism underlying the oncogenic effect of FTO is based on its capability of MALAT1 demethylation and the regulatory functions on the MALAT/miR‐384/MAL2 axis, which are three of the crucial molecular biomarkers clinically relevant to bladder cancer." (PMID 33634966, 2021). "FTO, MALAT1, miR‐384, and MAL2 are all clinically relevant biomarkers in bladder cancer, among which the expression of FTO influences the prognosis of bladder cancer patients." (PMID 33634966, 2021).
hepatocellular carcinoma (6 papers, 2009 to 2024). A malignant tumor that arises from hepatocytes. "IL7 and MAL2 promote Sorafenib resistance in hepatocellular carcinoma by enhancing JAK/STAT and PI3K/AKT signaling, while autophagy-inducing stapled peptides counteract this resistance by degrading resistance-related proteins and synergizing with Sorafenib." (PMID 39315094, 2024). "MAL2 has been reported to work as an essential component of the machinery for transcytosis in hepatoma HepG2 cells." (PMID 36341328, 2022). "To further confirm that MAL2 expression promotes actin-based protrusion formation, yet impairs cell migration, we expressed wild type MAL2 in the hepatoma-derived Clone 9 cells." (PMID 32059473, 2020). "MAL2 has consistently been found in lipid raft-containing membrane fractions in hepatoma HepG2 cells as well as in human thyroid epithelial cells." (PMID 19175940, 2009). "In HepG2 hepatoma cells, MAL2 resides exclusively within lipid rafts, and represents an essential component for indirect basolateral-to-apical transcytosis, where it shows a highly dynamic subcellular localisation." (PMID 19175940, 2009). "Nevertheless, recent studies suggest that MAL2 may be a promising target for cancers such as colorectal cancer and hepatocellular carcinoma.Therefore, the function of MAL2 in different cancers are inconsistent, indicating that the role of MAL2 may be organ-dependent." (PMID 37480012, 2023). "Because we have been investigating MAL2’s biochemical and functional properties in polarized hepatic cells, we chose to assess its potential role in mediating carcinogenesis in hepatocellular carcinoma (HCC)." (PMID 32059473, 2020). "To further examine whether MAL2 expression is potentially tumor suppressive, we assayed common oncogenic properties of three hepatic-derived cells: polarized, hepatic WIF-B cells, nonpolarized, HCC-derived Hep3B cells and nonpolarized, hepatoma-derived Clone 9 cells." (PMID 32059473, 2020).
colorectal cancer (5 papers, 2010 to 2023). A primary or metastatic malignant neoplasm that affects the colon or rectum. "Similar effects were observed for exogenous MAL2 in prostate, pancreatic, lung, and liver cancer cells; for exogenous MALL in colorectal cancer cells; and for CMTM8 in liver, pancreatic, and urothelial cancer cells." (PMID 37345137, 2023). "In the present study, we investigated the expression of MAL2 and TPD52 in colorectal cancer clinical specimens and the potential clinical significance." (PMID 28562687, 2017). "However, the expression of MAL2 in colorectal cancer has not been still investigated, and its potential clinical significance remains unclear." (PMID 28562687, 2017).